GJB6 (gap junction protein beta 6)
Diseases named in the same sentence as GJB6 in open-access papers (continued):
Sharing a sentence is not in itself a finding about the gene and the disease.
nonsyndromic hearing loss (5 papers, 2011 to 2021). "Although hundreds of genes have been reported to be associated with nonsyndromic hearing loss (NSHL), GJB2, GJB6, SLC26A4, and mitochondrial (mt) MT-RNR1 and MTTS are the major contributors." (PMID 28273078, 2017). "The most common form of hereditary nonsyndromic hearing loss is autosomal recessive deafness 1A (DFNB1A, MIM#220290) caused by pathogenic variants in the GJB2, GJB6, and GJB3 genes encoding connexin 26 (Cx26), connexin 30 (Cx30), and connexin 31 (Cx31) proteins, respectively." (PMID 31015822, 2019). "As for genetic factors of nonsyndromic deafness in China, the average value of variant in GJB2 seems to be the most common (23.37%), followed by SLC26A4 (14.74%), mtDNA 12SrRNA A1555G ( 2.44%), GJB3 (1.97%) and GJB6 (1.33%) genes." (PMID 23554706, 2011).
ectodermal dysplasia (4 papers, 2022 to 2023). "GJB2 and GJB6 have also been associated with ichthyoses, keratoderma, and ectodermal dysplasias." (PMID 37239394, 2023). "Dystrophic or otherwise abnormal nails were evident in 17 of 18 subjects with pathogenic WNT10A or GJB6 variants but in none of 161 children with EDA variants underlying X-linked hypohidrotic ectodermal dysplasia." (PMID 36421794, 2022).
keratitis (4 papers, 2015 to 2026). A corneal disease that is characterized by inflammation of the cornea. "Mutations in GJB2, GJB6, and GJA1 result in keratitis, corneal opacity, skin disorders, and hearing loss." (PMID 34381080, 2021). "Germline variants in GJB6 and GJB2 (connexin 26), which are similarly enhanced in this subpopulation, cause keratitis-ichthyosis-deafness syndrome, typified by transient inflammatory erythrokeratoderma." (PMID 30355494, 2018).
melanoma (4 papers, 2013 to 2024). A malignant, usually aggressive tumor composed of atypical, neoplastic melanocytes. "The expression of Cx26 and Cx30 (GJB6) was elevated in the epidermal layers adjacent to tumors from melanoma patients and was correlated with metastasis." (PMID 30642339, 2019).
cataract (3 papers, 2016 to 2025). Partial or complete opacity of the crystalline lens of one or both eyes that decreases visual acuity and eventually results in blindness. "Variants in GJA3 have been associated with cataracts in humans, while mutations in GJB2 and GJB6, encoding for connexin-26 and 30, respectively, transmembrane proteins involved in the formation of gap junction in the cochlea, are known for their critical roles in hearing." (PMID 40025542, 2025).
Stroke (3 papers, 2018 to 2021). Sudden impairment of blood flow to a part of the brain due to occlusion or rupture of an artery to the brain. "Interestingly, several genes such as GAD1, GJB6, GJD2, and AQP4 known to be induced or repressed by those early events of stroke are regulated in an opposite manner by PACAP which contributes to explain how PACAP protects the brain after stroke." (PMID 33551991, 2020).
age-related hearing loss (2 papers, 2022 to 2024). "Indeed, deletion of GJB6, with the consequent Cx30 ablation, makes the cochlear structure more vulnerable to senescence, worsening presbycusis, influencing Cx26 expression, and, in turn, exacerbating oxidative stress, inflammation, and vascular dysfunctions during cochlear senescence." (PMID 36016655, 2022).
colon cancer (2 papers, 2014 to 2022). "Results of qPCR suggested that the levels of GJB6 were distinguished according to the status of KRAS-mutation, though we didn’t detect the signals of NTNG1 in colon cancer cell lines." (PMID 35774610, 2022).
ischemic stroke (2 papers, 2020 to 2023). A stroke disorder caused by obstruction of blood flow to the brain, due to thrombotic (local blood clot formation) or embolic (due to a blood clot or other material traveling from another site) event. "Gjb6 was significantly downregulated after ischemic stroke, which was consistent with the change in Etnppl expression." (PMID 36794261, 2023).
autosomal recessive deafness 1A (1 paper, 2019). "The aim of this study is to compare the performance of the in silico pathogenicity prediction tools by testing the missense variants in GJB2 (Cx26), GJB6 (Cx30), and GJB3 (Cx31) genes associated with the autosomal recessive deafness 1A." (PMID 31015822, 2019).
Down syndrome (1 paper, 2025). "Other alterations included compound GJB2/GJB6 mutations, DIABLO gene variants, and Down syndrome (n = 2 each, 2.4%)." (PMID 41303275, 2025).
epidermal disease (1 paper, 2024). A skin disease that involves the epidermis. "In addition to Cx26, mutations in GJB6, GJB4, GJB3 and GJA1, encoding Cx30, Cx30.3, Cx31 and Cx43, respectively have also been linked to diverse epidermal diseases." (PMID 38827992, 2024).
erythrokeratoderma (1 paper, 2022). An umbrella term for a group of rare genetic skin disorders characterized by well-demarcated plaques of reddened, dry and thickened skin. "At the beginning, Netherton syndrome and Erythrokeratoderma variabilis phenotypes were suspected, but no hair shaft abnormalities were found and no mutations in SPINK5 and EKV genes (GJB2, GJB3, GJB4, GJB6 and KDSR) were identified (data not shown)." (PMID 34983512, 2022).
hemorrhagic stroke (1 paper, 2023). A stroke caused by a bleed on the brain. "Agt and Itih3 was significantly upregulated after hemorrhagic stroke and Gjb6 showed the same tendency." (PMID 36794261, 2023).
Sepsis (1 paper, 2019). Sepsis is defined as life-threatening organ dysfunction caused by a dysregulated host response to infection. "Interestingly, several of the genes linked to glucocorticoid signaling (Arl4d, Cdkn1a, Ddit4, Fkbp5, Gjb6, Il6ra, Klf15, Nfkbia, Rhob, Sdc4, Sgk1, Sult1a1, Tob2, Wipf3) and apoptotic process were still upregulated 4 days post-sepsis." (PMID 31278440, 2019).
tumor (11 papers, 2005 to 2025). "GJB6 (harboring cg03473518) encodes a tumor‐suppressive gap junction protein and may prevent GBM growth via rewiring glucose metabolism and inhibiting stemness." (PMID 37830163, 2024). "The same study also revealed a bidirectional interaction between cancer and the microenvironment, with an increase in Cx43, Cx26, and GJB6 (Cx30) proteins in the adjacent epidermis, and in Cx43 in lymphoid vessels close to the tumor." (PMID 40227837, 2025). "It seems clear that the mRNA expression of a number of connexins are dramatically changed in tumours (up to 289-fold in the case of GJB6/Cx30 in LUAD)." (PMID 30845770, 2019). "In the validation cohort from GSE53757, TNFSF13B, CASP5, and GJB6 correlated positively with tumor stages, while FREM1 negatively correlated with tumor stages." (PMID 32311223, 2020). "We analyzed the gene expression levels of 12 hub genes with clinical tumor stages and found that TNFSF13B, CASP5 and GJB6 correlated positively with tumor stages, while FREM1 showed negative associations with tumor stages." (PMID 32311223, 2020). "However, again, the overall patient survival was not correlated with the presence of GJB6 deletions (517 tumours from TCGA and 67 tumours from REMBRANDT) or GJB6 mRNA expression (in patients from TCGA)." (PMID 30814684, 2019).
cancer (7 papers, 2014 to 2025). A tumor composed of atypical neoplastic, often pleomorphic cells that invade other tissues. "The heat map shows positive correlation between GJB2 and the five genes (GJB6, KRT6A, KRT6B, KRT14, and IVL) in pan-cancer." (PMID 37427102, 2023). "GJB6 was conserved only in EGFR-mut and KRAS-mut cancers while the latter also conserved GJB3." (PMID 36612014, 2022).
skin disorder (7 papers, 2011 to 2024). Any deviation from the normal structure or function of the skin or subcutaneous tissue that is manifested by a characteristic set of symptoms and signs. "Up to now, at least 20 genes of human connexins are known, but skin disorders are only connected with mutations in GJB2 (Cx26), GJB6 (Cx30), GJB3 (Cx31), GJB4 (Cx30.3), and GJA1 (Cx43)." (PMID 25575739, 2015).
infection (3 papers, 2011 to 2024). The state of being infected such as from the introduction of a foreign agent such as serum, vaccine, antigenic substance or organism. "The two largest infection-specific clusters exhibited distinct gene expression patterns, with cluster 0 and cluster 6, enriched in Zeb2 and Gjb6 expression, respectively." (PMID 38767331, 2024). "We observed two infection-specific keratinocyte populations enriched in Zeb2 and Gjb6 expression, respectively, as early as 4 days post-wounding." (PMID 38767331, 2024).
autosomal recessive hereditary diseases (1 paper, 2021). "Similar reports have shown GJB2/GJB6 and GJB2/GJB3 variants in 11% of deaf children, and genetic interaction between GJB2 and GJB3 in three unrelated families with autosomal recessive hereditary diseases." (PMID 34276761, 2021).
peripheral nervous system disease (1 paper, 2023). "A number of these, including connexin 26 (Cx26)/GJB2, Cx29/Cx31.3/GJC3, Cx30/GJB6, Cx32/GJB1, Cx36/GJD2, Cx43/GJA1, Cx45/GJC1 and Cx47/GJC2 are expressed in the central and/or peripheral nervous system and mutations in a number of these cause central and/or peripheral nervous system disease." (PMID 37189458, 2023).
GJB6 also shares sentences with these, for which no sentence is quoted: Hearing impairment (25 papers); depression (8); epilepsy (7); breast carcinoma (4); glioblastoma (4); Hyperkeratosis (4); Parkinson disease (4); alopecia (3); Alzheimer disease (3); cognitive deficits (3); erythrokeratodermia variabilis (3); experimental autoimmune encephalomyelitis (3); ichthyosis (3); cardiovascular disease (2); endothelial dysfunction (2); gastric cancer (2); Hypertension (2); lung adenocarcinoma (2); Obesity (2); psoriasis (2); psychiatric diseases (2); absence seizures (1); acute stress disorder (1); age (1); Alport syndrome (1); Alstrom syndrome (1); amyotrophic lateral sclerosis (1); Anxiety (1); autosomal dominant deafness (1); autosomal-dominant inherited disorder (1).
A further 46 diseases each share a sentence with GJB6 in 1 paper.